METTL14 (methyltransferase 14, N6-adenosine-methyltransferase non-catalytic subunit)
Diseases named in the same sentence as METTL14 in open-access papers (continued):
Sharing a sentence is not in itself a finding about the gene and the disease.
tumor (continued). "Furthermore, METTL14 knockdown partially reversed the effect of FTO deletion on tumor growth." (PMID 33846348, 2021). "Therefore, we speculate that the METTL14/CCL5/Tregs axis might be a potential pivotal regulated pathway of tumor immunity and progression in ccRCC, a subject worthy of further in-depth study." (PMID 34122497, 2021). "In summary, the results demonstrated that METTL14 might be considered as a tumor suppressor in GC." (PMID 33314339, 2021). "Similarly, emerging evidences have also indicated that METTL14 could exert as either a oncogene or tumor suppressor." (PMID 32419773, 2020). "Therefore, METTL14 may exert anti-tumor activity via targeting and down-regulating oncogenes or oncogenic lncRNAs in these pathways." (PMID 32111213, 2020). "In vivo, SMURF1 silencing restored METTL14 expression and attenuated PSMC5-driven tumor growth and lung metastasis." (PMID 42212325, 2026). "Knockdown of METTL14 significantly suppresses GBM proliferation, migration, and immune evasion while slowing tumor growth in murine models." (PMID 41164187, 2025). "While most previous studies recognize that METTL3 and METTL14 are important to cancer cell survival, one study showed that METTL3 enhanced the tumor suppression activity of p5346." (PMID 38853928, 2025). "Meanwhile, we also observed that SLC27A5 depletion markedly enhanced the tumor-forming capacity in HepG2 and SNU449 cells, which was rescued by the re-expression of METTL14-US." (PMID 40290127, 2025). "Upregulated METTL14 subsequently enhances FAT4 expression through an m6A-YTHDF1-dependent pathway, exerting tumor-suppressive effects." (PMID 41164187, 2025). "These systems can also be leveraged to reprogram macrophages, enhancing the stability of METTL14 in vivo, inhibiting the TLR4 pathway, regulating macrophage polarization, and remodeling the TME to improve anti-tumor responses." (PMID 40380260, 2025). "For example, in tumor cells, the m6A writers METTL3 and METTL14 suppress the expression of chemokines CXCL9 and CXCL10, leading to immune exclusion." (PMID 40176140, 2025). "Evidence has shown that METTL14 promotes m6A-dependent degradation of PDCD1 mRNA, thereby downregulating PD-1 expression, sustaining CD8+ T cell activation, and suppressing tumor progression." (PMID 41164187, 2025). "The specific depletion of the m6A methylase METTL14 in macrophages disrupts the differentiation of CD8+ T cells, which in turn weakens the ability of these cells to clear tumours." (PMID 40356909, 2025). "Overall, the roles of METTL3 and METTL14 in regulating GPX4 and SLC7A11 are central to current research on m6A methyltransferase-mediated ferroptosis and its impact on tumor growth." (PMID 40271153, 2025). "CEBPA participates in chemoresistance through METTL3/METTL14/BHLHB9 in vivo, which accelerated the tumor growth." (PMID 40297811, 2025). "As an essential component of the m6A methyltransferase complex, METTL14 cooperates with METTL3 and also significantly contributes to tumor progression in various cancer types." (PMID 40640957, 2025). "Current research on methyltransferases, particularly METTL3, METTL14, and WTAP, primarily focuses on their roles in regulating ferroptosis and tumor growth." (PMID 40271153, 2025). "Taken together, these studies reveal that the interplay between METTL3, METTL14 and WTAP fine-tunes m6A methylation activity, influencing the balance between CSC maintenance and differentiation across tumor types." (PMID 41228380, 2025). "Reducing the expression levels of METTL14 and WTAP has limited effects on the tumour development and behaviour of endometrioid epithelial OC cells cultured in vitro." (PMID 40356909, 2025).
tumor (continued). "It was discovered in a tumor-based study that METTL3 and METTL14 act on miR-380-3p through a m6A modification-dependent mechanism." (PMID 39904996, 2025). "In contrast, METTL14 is down-regulated in HCC, and METTL14 expression can induce an increase of primary microRNA 126 (pri-miR-126) expression to suppress tumor metastasis." (PMID 40483535, 2025). "It catalyzes the asymmetric dimethylation of METTL14 at arginines 442 and 445 within its C‐terminal RGG motif, thereby enhancing METTL14's activity and promoting tumor cell proliferation and transformation." (PMID 41256732, 2025). "Regarding protein expression, varying intensities of METTL3, METTL14 and CBLL1 staining was observed in the nuclei of tumour epithelial cells by IHC." (PMID 41310336, 2025). "In this study, the expressions of WTAP, METTL14, YTHDF3 were inhibited in tumor tissues, the decrease of WTAP levels was most apparent." (PMID 39744575, 2025). "In breast cancer, the expression levels of METTL14 and ALKBH5 regulate each other and together promote tumour development by regulating m6A modification levels in specific transcripts associated with epithelial-mesenchymal transition (EMT) and angiogenesis." (PMID 40356909, 2025). "Additional researches indicate that knockdown of METTL14, NAT10, and NSUN2 in OS cell lines significantly inhibits tumor growth in nude mice 11-13." (PMID 39897026, 2025). "The METTL3/METTL14 complex can activate the AKT pathway by promoting the expression of ADAMTS9 and miR-380-3p to promote tumor angiogenesis and EMT." (PMID 41194259, 2025). "More importantly, because METTL14-mediated m6A modification enhances PD-L1 expression and promotes an immunosuppressive microenvironment, inhibition of METTL14 may not only directly impair tumor proliferation but also downregulate PD-L1 expression to improve T cell–mediated antitumor immunity." (PMID 41164187, 2025). "Recent studies highlight its pivotal function in tumor immunity: METTL14 shapes T cell differentiation, CD8+ T cell activation, and the activity of macrophages and NK cells, thereby remodeling the tumor immune microenvironment." (PMID 41164187, 2025). "A few METTLs, such as METTL1, METTL14 and METTL16, also showed oncogenic effects, to systematically delineate the distinct roles of METTL family members across tumor types, we generated a comprehensive schematic." (PMID 41194259, 2025). "On the other hand, emerging evidence suggests METTL14 and ZC3H13 function as tumor suppressors in triple-negative breast cancer." (PMID 41157107, 2025). "Silencing METTL14 significantly inhibited TNBC cell growth and invasion in vitro, as well as suppressed tumour growth." (PMID 38263865, 2024). "The methytransferase METTL14 is reduced in hepatocellular carcinoma, and promotes pri-miR-126 processing through an m6A/DGCR8-dependent manner, thus acting as a tumor suppressor." (PMID 39457524, 2024). "Analysis of the TCGA database showed that in addition to METTL3 and METTL14, the expression of the novel “m6A writer” METTL16 was also decreased in tumor tissue." (PMID 38334797, 2024). "Targeted deletion of the m6A methyltransferase METTL14 specifically in macrophages drives the differentiation of CD8+ T cells towards a dysfunctional phenotype, thereby compromising their efficacy in tumor elimination." (PMID 39199429, 2024). "Mechanistically, we found that METTL14 up-regulates G6PD expression through an m6A-IGF2BP2-dependent pathway, contributing to tumor growth and metastasis in glycolytic microenvironments." (PMID 39138186, 2024). "For example, down-regulation of METTL14 is found in metastatic HCC, and this change can be used to determine the prognosis of the tumor." (PMID 39033180, 2024). "Downregulation of METTL14 dysregulates the circSTX6/HNRNPD/ATF3 axis, accelerates HCC proliferation and tumorigenicity, and enhances tumor metastasis." (PMID 39229278, 2024).
tumor (continued). "In contrast to the previous studies, METTL14 stabilized PTEN, leading to tumor progression inhibition and suggesting a potential therapeutic target." (PMID 38503745, 2024). "As a result, in CRC, METTL3, METTL14, WTAP, IGF2BP3, YTHDC1, and FTO orchestrate tumor angiogenesis through diverse pathways and mechanisms, thereby affecting the initiation, progression, and prognosis of CRC." (PMID 39295872, 2024). "To evaluate the expression of METTL14 in NB cells, we utilized the Cancer Cell Line Encyclopedia (CCLE) database to compare METTL14 levels in various tumor cell lines." (PMID 38649363, 2024). "We established a subcutaneous tumour model and tail vein lung metastasis model in BALB/C nude mice using NPC cells with either METTL14 overexpression or knockdown to further assess the influence of METTL14 on NPC growth and metastasis in vivo." (PMID 39021049, 2024). "METTL14, through the modulation of TGFβ via the RhoA and PI3K-AKT pathways, contributes to tumor angiogenesis and progression." (PMID 38408075, 2024). "On the other hand, overexpression of METTL14 in cells can inhibit the EGFR/PI3K/AKT signaling pathway in an m6A methylation-dependent manner, thereby suppressing tumor metastasis." (PMID 38965238, 2024). "METTL14, as an essential allosteric activator of METTL3, also plays a significant role in tumor progression across various cancer types." (PMID 39138186, 2024). "We next consulted proteomics data from the Clinical Proteomic Tumor Analysis Consortium (CPTAC) and TCGA-BRCA and found that METTL14 was significantly downregulated in TNBC tissues compared with non-TNBC tissues." (PMID 39563370, 2024). "This study has identified the critical role of up-regulated METTL14 in enhancing gene expression of G6PD, thereby promoting tumor growth and metastasis in LUAD." (PMID 39138186, 2024). "Among the changes, oncogenes such as ADAM19, EPHA3, and KLF4 showed increased expression, but tumor suppressors like CDKN2A and BRCA2 demonstrated decreased expression by inhibition of METTL3- or METTL14." (PMID 38398118, 2024). "IGF2BP1, HNRNPA2B1, FTO, WTAP promote the EC progression, but METTL3, METTL14, YTHDF2 work as tumor suppressors in EC." (PMID 39582531, 2024). "The m6A modification plays an indispensable role in maintaining the tumor infiltration and cytotoxicity of NK cells, primarily regulated by METTL3, METTL14, and YTHDF2." (PMID 39372415, 2024). "C1q+TAMs specifically express METTL14 and YTHDF2, and maintain the level of tumor infiltration and cytotoxicity of CD8+ T cells in a METTL14-dependent manner." (PMID 39372415, 2024). "Evidence suggests that METTL14 and METTL3 have different implications for poor tumor prognosis in CRC." (PMID 39033180, 2024). "For instance, most of the available urologic tumour studies have focused on popular methyltransferases and m6A binding proteins, such as METTL3, METTL14, YTHDFs and IGF2BPs." (PMID 37284313, 2023). "METTL14 can reduce the expression of miR-375 through m6A modification and indirectly promote the expression of downstream SOX12, thereby playing a tumor suppressor role." (PMID 37901333, 2023). "In the TIME, depletion of METTL3, or METTL14 depletion within CRC tumors, increases cytotoxic tumor-infiltrating CD8+ T cells and secretion of cytokines such as IFN-γ, CXCL9 and CXCL10, hence sensitizing tumors to PD-1 antibody treatment." (PMID 37015927, 2023). "Immunohistochemical images showed the expression levels of RBM15, VIRMA, YTHDC2, YTHDF2, METTL14, and IGF2BP2 proteins in tumor tissues." (PMID 36791151, 2023). "METTL14 is downregulated in macrophages of CRC, promoting tumor progression; this reveals a potential relationship between these cells and the infiltration of surrounding CD8+ T cells in the TME." (PMID 37965577, 2023). "Recently, the mechanism of METTL14 and WTAP methylation effects on tumour proliferation through the PI3K-AKT pathways in RCC has been demonstrated." (PMID 37284313, 2023).
tumor (continued). "Downregulation of METTL14 and overexpression of ITGB4 promote tumour invasion, metastasis, and the PI3K/AKT signaling in RCC." (PMID 37284313, 2023). "METTL14 modifies TGFβ through the RhoA and PI3K-Akt pathways, which are considered to be related to tumor angiogenesis and tumor progression." (PMID 38053093, 2023). "In tumor models, METTL3 and METTL14 were reported to redistribute and localize to the promoters or enhancers of SASP genes during the senescence process." (PMID 37015927, 2023). "METTL14-mediated m6A modification promotes the stability of the TRAF1 mRNA in an IGF2BP2-dependent manner, thereby significantly promoting tumor angiogenesis." (PMID 38053093, 2023). "Methyltransferase-like 14 (METTL14), as a core member of methyltransferases, is involved in tumor progression and metastasis." (PMID 37215454, 2023). "Mediated by YTDHF2, METTL3/METTL14 knockdown stabilizes STAT1 and Irf1 mRNAs, and promotes IFN‐γ‐STAT1‐Irf1 signaling, which in turn sensitizes tumor cells to PD‐1 inhibition." (PMID 36810108, 2023). "By regulating Pten mRNA for m6A modification via a YTHDF1-dependent mechanism, the downregulation of METTL14 in RCC inhibited Pten expression, leading to the progression of tumours through PI3K/AKT signaling." (PMID 37284313, 2023). "In general, METTL3, METTL14, IGF2BP1, FTO, and ALKBH increase the level of PD-L1 on the membrane and thereby promote tumor cell immune escape." (PMID 37485079, 2023). "Except METTL14, YTHDF2 and YTHDF3, all m6A related genes expression were significantly different between tumor and control group." (PMID 37194014, 2023). "Given that m6A writers are important for cancer progression, usually as a tumor promoter during tumor progression, this study explored the expression of m6A writers, including METTL3, METTL14, and WTAP, in tumor and adjacent normal tissues." (PMID 35778697, 2022). "Here, we identified lncRNA methyltransferase-like 14 (METTL14) as a tumor-suppressor gene in BCa, acting to inhibit cell migration, invasion and epithelial–mesenchymal transition (EMT) as well as tumor metastasis." (PMID 36288387, 2022). "Overall, these results showed that the expression of METTL3, METTL14, and WTAP were higher in tumor samples than in the adjacent normal samples." (PMID 35778697, 2022). "Compared with normal counterparts, 4 DEMGs (FTO, ZC3H13, METTL14 and RBM15B) were significantly down-regulated in tumor samples, while the remaining 11 genes were upregulated in tumor samples." (PMID 36536402, 2022). "First of all, the expression level of METTL14 was identified to be obviously decreased in HCC, which closely correlated with clinicopathological factors, including tumor stage and prognosis." (PMID 35974338, 2022). "The results from our and other laboratories showed that METTL14 was downregulated in CRC, HCC and GC, repressed tumor proliferation and metastasis and correlated negatively with tumor prognosis." (PMID 35974338, 2022). "METTL3, METTL14, METTL16, YTHDC1, YTHDC2, and ZC3H13 expression levels were significantly greater in tumor tissues (p < 0.05)." (PMID 36091006, 2022). "By regulating the microprocessor protein DGCR8, METTL14 promotes the maturation of PRI-mir126 into mature mir126, a tumor suppressor of HCC metastasis." (PMID 36147735, 2022). "METTL14 can regulate the expression of PERP, USP48, PTEN, and SOX4 in a m6A-dependent manner and inhibit tumor proliferation, invasion, migration, metastasis and drug resistance." (PMID 35945641, 2022). "It was proved that METTL14 impedes the metastasis of CRC cells and exerts a tumor suppressor effect." (PMID 34904301, 2022). "METTL14, as the indispensable allosteric activator of METTL3, has been shown to play an important role in tumor progression in many types of cancers." (PMID 35354789, 2022). "METTL14 overexpression reduces PERP mRNA and protein levels and promotes tumor cell migration and colony formation." (PMID 35115038, 2022).
tumor (continued). "The stability of USP48 mRNA is reduced due to decreased m6A modification of METTL14 and leads to the degradation of its downstream target gene SIRT6, which ultimately enhances aerobic glycolysis in tumor cells." (PMID 35784761, 2022). "To further validate the results, we obtained 60 paired tumor tissues and adjacent normal tissues of ESCC, and qRT-PCR was used to determine the expression pattern of METTL3, METTL14, WTAP, FTO, ALKBH5, YTHDF1 and YTHDF2." (PMID 35399719, 2022). "On the other hand, METTL14 can regulate the expression of miR-146A-5p and the lncRNA OIP5-AS1 and thus promote tumor development." (PMID 35945641, 2022). "Although METTL3, METTL14 and WTAP can form RNA methyltransferase complexes, which regulate the fate of tumour development, studies have shown that METTL3 and METTL14 also have independent regulatory functions in regulating transcription." (PMID 36434140, 2022). "In short, METTL14 is low-expressed in BCa cell lines and represses BCa cell migration, invasion and EMT in vitro and tumor metastasis in vivo." (PMID 36288387, 2022). "This study verified that METTL14 expression is down-regulated in BCa cells lines, prohibiting the migration, invasion and EMT of BCa cells, as well as tumor metastasis." (PMID 36288387, 2022). "We identify 12 significantly mutated genes and 5 focal CNA regions, and demonstrate common mutations in post-transcriptional modification-related potential driver genes METTL14 and RBM10 in pCCA tumours." (PMID 35650238, 2022). "This target can act as a tumor suppressor or an oncogene, and the abnormal expression of METTL3 or METTL14 biases them toward the regulation of a certain target, thereby exhibiting the opposite effect." (PMID 36561529, 2022). "Downregulation of METTL14 and ZC3H13 in BCa, act as tumor suppressor, has been found in breast cancer and poor prognosis is predicted." (PMID 35784761, 2022). "Mettl14 knockdown in macrophages suppressed the antitumour activity of CD8+ T cells and improved tumour growth." (PMID 36407103, 2022). "Overall, METTL3, METTL14, VIRMA, and ALKBH5 immunoexpression levels differed significantly between tumor and normal tissues." (PMID 35048498, 2022). "And in mechanism, IFN-γ-Stat1-Irf1 signaling was activated after the depletion of METTL3 and METTL14, leading to the increased secretion of IFN-γ, and finally enhanced the CD8+T cell-mediated anti-tumor response in the tumor microenvironment." (PMID 36058919, 2022). "Among the three major components of the writer complex, only METTL3 was upregulated in LUAD as determined by ELISA; METTL14 and WTAP were expressed at similar levels in adjacent and tumor tissues." (PMID 35078505, 2022). "Inhibition METTL14 expression results in a significant decreasing of the half-life of MYB and MYC transcripts, thus inhibiting tumor progression." (PMID 35022030, 2022). "Hypoxia-mediated ALKBH5 is reported to significantly accelerate TAM recruitment and immunosuppression and the m6A methyltransferase METTL14 in TAMs induces CD8+ T cell dysfunction and tumor progression." (PMID 35794625, 2022). "In addition, the deficiency of MettL3 or Mettl14 in tumors results in enhancing cytotoxic tumor-infiltrating CD8+ T cells, and increasing the secretion of IFN-c, Cxcl9 and Cxcl10 in TME in vivo, which proves that the immune system and tumor microenvironment have metastasized in tumor m6A mRNA." (PMID 35069586, 2021). "The levels of METTL3 and METTL14 in AML show significant changes, which affects the proliferation of AML cells and the process of tumor progression." (PMID 34206803, 2021). "The function of METTL14 was further evaluated in the METTL14-knockdown CRC xenograft, which indicated that suppression of METTL14 elevated tumor growth, as reflected by tumor size, volume and weight." (PMID 34916487, 2021).